UQCC2 (ubiquinol-cytochrome c reductase complex assembly factor 2)
Description:
Required for the assembly of the ubiquinol-cytochrome c reductase complex (mitochondrial respiratory chain complex III or cytochrome b-c1 complex). Plays a role in the modulation of respiratory chain activities such as oxygen consumption and ATP production and via its modulation of the respiratory chain activity can regulate skeletal muscle differentiation and insulin secretion by pancreatic beta-cells. Involved in cytochrome b translation and/or stability.
Synonyms: C6orf125; MNF1; MGC14833; bA6B20.2; M19; Cbp6; C6orf126; MC3DN7
Tractability: PROTAC: ubiquitination databases record sites on it; its protein half-life has been measured.
Gene: Protein-coding gene on chromosome 6 (33,690,635 to 33,711,727, reverse strand). Ensembl gene ENSG00000137288.
Subcellular location: Mitochondrion matrix, mitochondrion nucleoid; Mitochondrion; Mitochondrion intermembrane space; Mitochondrion matrix; Mitochondrion inner membrane
Subcellular location (Human Protein Atlas): Mitochondria; Nuclear bodies
Pathways (Reactome):
Metabolism: Complex III assembly
Gene Ontology:
Molecular function: protein binding
Biological process: mitochondrial respiratory chain complex III assembly; positive regulation of mitochondrial translation; regulation of oxidative phosphorylation; regulation of insulin secretion; regulation of skeletal muscle cell differentiation
Cellular component: mitochondrial nucleoid; mitochondrion; mitochondrial inner membrane; mitochondrial intermembrane space; mitochondrial matrix
Genetic constraint (gnomAD): Loss-of-function variants: 20 observed, 20.78 expected, observed/expected ratio (o/e) 0.96, 90% interval 0.68 to 1.4. The upper end of that interval is the gene's LOEUF score, 1.4, which puts it in group 5 of 6, group 1 being the genes least tolerant of losing a copy. Missense variants: 135 observed, 167.18 expected, observed/expected ratio (o/e) 0.81, 90% interval 0.7 to 0.93. Synonymous variants: 57 observed, 64.96 expected, observed/expected ratio (o/e) 0.88, 90% interval 0.71 to 1.09.
Gene-disease validity (ClinGen):
ClinGen rates the evidence that UQCC2 causes each of these diseases.
mitochondrial disease (autosomal recessive): Moderate.
Homologues: Orthologues: chimpanzee UQCC2 (99% identical), macaque UQCC2 (96% identical), rabbit UQCC2 (93% identical), guinea pig UQCC2 (91% identical), mouse Uqcc2 (91% identical), pig UQCC2 (91% identical), rat Uqcc2 (90% identical), rat Uqcc1-ps1 (85% identical), dog UQCC2 (75% identical), tropical clawed frog uqcc2 (63% identical), zebrafish uqcc2 (61% identical), Caenorhabditis elegans Y48A5A.3 (19% identical).
Diseases named in the same sentence as UQCC2 in open-access papers:
UQCC2 is named in the same sentence as 19 diseases in open-access papers, as found by Europe PMC text mining. Sharing a sentence is not in itself a finding about the gene and the disease. The quoted sentences say what the papers report.
breast carcinoma (1 paper, 2022). "MicroRNA miR-663 targets the mitochondrial respiratory complex III assembly factor ubiquinol-cytochrome c reductase complex assembly factor 2 (UQCC2) transcript and regulates breast cancer cell proliferation." (PMID 35178385, 2022).
celiac disease (1 paper, 2018). An autoimmune genetic disorder with an unknown pattern of inheritance that primarily affects the digestive tract. "HiSeeker detected an SNP interaction (rs375555, rs542441) on chromosome 6, in which rs542441 in gene UQCC2 has a high probability of being associated with Celiac disease." (PMID 30072632, 2018).
Cirrhosis (1 paper, 2022). A chronic disorder of the liver in which liver tissue becomes scarred and is partially replaced by regenerative nodules and fibrotic tissue resulting in loss of liver function. "Therefore, it can be speculated that abnormal expression of the UQCC2 gene can lead to liver damage and cirrhosis by affecting the metabolic process of the respiratory chain." (PMID 35646080, 2022).
lactic acidosis (1 paper, 2013). Metabolic acidosis characterized by the accumulation of lactate in the body. "We have shown that mutations in UQCC2 cause human complex III deficiency in a patient with neonatal lactic acidosis and renal tubulopathy." (PMID 24385928, 2013). "We identified a causative homozygous UQCC2 (MIM 614461) splicing mutation in a patient with severe intrauterine growth retardation, neonatal lactic acidosis and renal tubular dysfunction associated with complex III deficiency." (PMID 24385928, 2013).
liver cancer (1 paper, 2022). An epithelial or non-epithelial malignant neoplasm that arises from the liver. "Given that UQCC2 is a downregulated gene in liver cancer tissue, it can be speculated that the damage caused by this metabolism contributes to the occurrence of liver cancer." (PMID 35646080, 2022).
sarcoidosis (1 paper, 2025). Sarcoidosis is a multisystemic disorder of unknown cause characterized by the formation of immune granulomas in involved organs. "Among them, there were 14 genes (ABT1, BTN2A2, C2orf74, CCDC88B, FAM213A, MDH2, METTL21B, PRSS16, RP3-473L9.4, TCF19, TSFM, UBASH3A, UQCC2, ZSCAN26) associated with sarcoidosis risk consistently across these tissues." (PMID 40075078, 2025). "In addition, our TWAS pinpointed many tissue-specific sarcoidosis-associated genes and found expressions of 14 genes (ABT1, BTN2A2, C2orf74, CCDC88B, FAM213A, MDH2, METTL21B, PRSS16, RP3-473L9.4, TCF19, TSFM, UBASH3A, UQCC2, ZSCAN26) associated with sarcoidosis across all three target tissues." (PMID 40075078, 2025).
cancer (1 paper, 2022). A tumor composed of atypical neoplastic, often pleomorphic cells that invade other tissues. "Unusually, by direct targeting the 3′UTR of ubiquinol-cytochrome C reductase complex assembly factor 2 (UQCC2), miR-663 stabilizes the UQCC2 transcripts, thus improving the function of ETC complexes in cancer progression." (PMID 35326131, 2022).
UQCC2 also shares sentences with these, for which no sentence is quoted: 3-methylglutaconic aciduria type 1 (1 paper); Cognitive impairment (1); depressive disorder (1); diabetes (1); Intellectual disability (1); melanoma (1); neurofibroma (1); neurofibromatosis (1); pigmentary changes (1); plexiform neurofibroma (1); prion disease (1); tumor (1).